SIRT1 (sirtuin 1)
Diseases named in the same sentence as SIRT1 in open-access papers (continued):
Sharing a sentence is not in itself a finding about the gene and the disease.
sarcopenia (37 papers, 2014 to 2025). Progressive decline in muscle mass due to aging which results in decreased functional capacity of muscles. "Mitochondrial energy metabolism dysfunction is a key mechanism underlying sarcopenia, and SIRT1 plays a crucial regulatory role in skeletal muscle metabolism." (PMID 40661078, 2025). "Collectively, functional decline of the SIRT1–PGC-1α–NRF1/2–TFAM axis constitutes a central event underlying mitochondrial biogenic failure in sarcopenia and represents a promising therapeutic target." (PMID 41568005, 2025). "Bring together, all these findings suggest that SIRT1 activation plays a pivotal role in the protection against age associated sarcopenia." (PMID 36818553, 2023). "SIRT-1 has emerged as a major therapeutic target for aging and age-associated diseases, including sarcopenia." (PMID 25361036, 2014). "This study not only contributes to our understanding of the mechanisms underlying the relationship between vitamin D and sarcopenia but also reveals the potential of vitamin D and Sirt1 activation as therapeutic targets for the prevention and management of sarcopenia." (PMID 40168539, 2025). "Additionally, we evaluated the effects of Sirt1 overexpression in MSCs on muscle mass, fiber type, senescence markers, and muscle regeneration in the context of 1,25(OH)2D deficiency-induced sarcopenia." (PMID 40168539, 2025). "Mechanically, berberine alleviated muscle tissue loss in sarcopenia via SIRT1/mitophagy pathway." (PMID 37483428, 2023). "Interestingly, frailty and sarcopenia are associated with oxidative stress and chronic, low-grade inflammation, both of which are counteracted by SIRT1." (PMID 35883477, 2022). "Therefore, understanding how oxidative stress modulates SIRT-1 is crucial to unraveling the mechanisms underlying sarcopenia." (PMID 25361036, 2014). "Therefore, we hypothesized that 1,25(OH)2D upregulates Sirt1 in myoblasts via VDR signaling and that Sirt1 overexpression in MSCs may prevent sarcopenia induced by 1,25(OH)2D deficiency." (PMID 40168539, 2025). "Therefore, activation of SIRT1 and 3 may avoid aging-associated sarcopenia and further help individuals to exercise, which in turn may further increase SIRT1 and 3, provoking a beneficial loop that may counteract aging and its related diseases." (PMID 31557786, 2019). "It provides an experimental basis for exploiting active vitamin D and Sirt1 activation clinically to prevent sarcopenia." (PMID 40168539, 2025). "This suggests that Sirt1 activation suppresses muscle cell senescence and related inflammation, representing an attractive sarcopenia strategy." (PMID 40168539, 2025). "In this study, we aimed to investigate the role of vitamin D and its interaction with Sirtuin 1 (Sirt1) in the development of sarcopenia." (PMID 40168539, 2025). "Several studies suggest that SIRT1 has strong anti-inflammatory effects as it can suppress the expression of inflammatory cytokines, counteracting the progression of muscle aging and sarcopenia." (PMID 40564069, 2025). "This underlines the beneficial effects of 1,25(OH)2D on muscle and highlights the Sirt1 axis as a promising target for sarcopenia therapies." (PMID 40168539, 2025). "This study examines the role of Sirtuin 1 (Sirt1) and its regulation by vitamin D in preventing sarcopenia." (PMID 40168539, 2025). "This pathway’s disruption, as observed in our 1α-hydroxylase knockout mice, led to reduced Sirt1 expression, contributing to sarcopenia." (PMID 40168539, 2025). "Sirtuins, such as SIRT1, are integral to processes that are central to muscle ageing and the pathology of sarcopenia." (PMID 39276001, 2024). "The age-related decrease in SIRT1 and SIRT3 levels is linked to the development of sarcopenia and age-related muscle dysfunction." (PMID 38004107, 2023).
sarcopenia (continued). "Herein, we constructed sarcopenia mice model, which was treated with berberine and/or SIRT1/mitophagy inhibitors, and the activity of SIRT1/mitophagy signaling pathway was identified." (PMID 37483428, 2023). "Sirtuins are considered an emerging therapeutical target in sarcopenia, and the circumstance that resveratrol is a strong activator of SIRT1 has boosted research on the putative anti-sarcopenic action of resveratrol." (PMID 37242251, 2023). "Understanding the precise role of berberine in treating sarcopenia IR and the regulation of SIRT1/mitochondrial autophagy pathway will advance our knowledge of sarcopenia pathogenesis." (PMID 37483428, 2023). "In conclusion, berberine regulated sarcopenia related metabolic disorders, and its implied mechanism was activation of SIRT1/mitochondrial autophagy pathway." (PMID 37483428, 2023). "Several in vivo studies suggests that sarcopenia is characterized by a decrease in the activity and expression of SIRT1." (PMID 36818553, 2023). "The results showed that SIRT1/mitophagy signaling pathway was inhibited by d-galactose, which indicated that sarcopenia decreased the activity of SIRT1/mitophagy signaling pathway." (PMID 37483428, 2023). "Taken together, Berberine relieved IR in sarcopenia, and the relief of IR in sarcopenia by berberine depends on SIRT1/mitochondrial autophagy pathway." (PMID 37483428, 2023). "Recently, Myers and colleagues demonstrated, by using SIRT1 knockout mice, that SIRT1 presence is pivotal to avoiding muscle fatigue and sarcopenia." (PMID 31557786, 2019). "Our data, along with these observations, suggest that treatment with potent and specific activators of SIRT1 can offer new therapeutic approaches for treating muscular dystrophies, and perhaps sarcopenia." (PMID 25032964, 2014). "Furthermore, SIRT1 expression increases during exercise, strengthening muscle mass, improving satellite cell activity, and counteracting sarcopenia and fragility." (PMID 39846667, 2025). "SIRT1 is a promising target for the treatment and prognosis of sarcopenia." (PMID 41383117, 2025). "Additionally, Fructus Lycii (gouqi) has been shown to activate SIRT1, supporting its role in combating sarcopenia and promoting muscle health." (PMID 40661078, 2025). "We found that EA combined with SFN restored skeletal muscle function in sarcopenia by activating the AMPK/Sirt1/PGC-1α pathway, inhibiting oxidative stress, apoptosis, and inflammation levels in skeletal muscle cells, and increasing the number and function of skeletal muscle mitochondria." (PMID 38629101, 2024). "However, the role of TRIM16 in facilitating SIRT‐1 against sarcopenia requires further investigation." (PMID 39192479, 2024). "In this study, the combined intervention of EA and SFN in SAMP8 mice demonstrated that EA and SFN could inhibit the disease process of sarcopenia in mice by activating the AMPK/Sirt1/PGC-1α pathway." (PMID 38629101, 2024). "Meanwhile, SIRT1-mediated mitochondrial autophagy activation in sarcopenia IR is the main mechanism by which berberine ameliorates IR in sarcopenia, and that mitochondrial autophagy may play an important role in IR in sarcopenia." (PMID 37483428, 2023). "Our study establishes proof-of-concept to distinct the effect of berberine in sarcopenia IR, and provides strong evidence to support the hypothesis that berberine-induced SIRT1 triggers mitochondrial autophagy pathway and suppresses IR in sarcopenia." (PMID 37483428, 2023). "In addition, it provides experimental evidence that vitamin D has the potential to be developed as a therapeutic or preventive agent against sarcopenia through the stimulation of the VDR/SIRT1/SIRT3 axis." (PMID 38004107, 2023). "Interestingly, our results showed that berberine up-regulated the expression of SIRT, and SIRT inhibitors inhibited the effect of berberine, suggesting that berberine mainly inhibits sarcopenia by regulating SIRT1." (PMID 37483428, 2023).
sarcopenia (continued). "SIRT1/mitophagy inhibitors suppressed the effects of berberine in the treatment of sarcopenia." (PMID 37483428, 2023). "Another molecular mechanism that has been determined from preclinical research on sarcopenia is the favourable effects of herbal products on anti‐apoptotic signalling pathways via the activation of AMPK/Sirt1, as well as an increase in the expression of anabolic factors." (PMID 35961944, 2022). "Notably, three prominent metabolic regulators (AMPK, PGC-1α and SIRT1) apparently cooperate to hinder the progression of sarcopenia." (PMID 34881083, 2021). "It has been reported that activation of SIRT‐1 might ameliorate sarcopenia, glucocorticoids and disuse‐induced atrophy." (PMID 33751819, 2021). "Therefore, SIRT1 may influence skeletal muscle mitochondrial function and energy metabolism, and its activation shows significant promise for mitigating sarcopenia." (PMID 41383117, 2025). "Thus, SIRT1 and autophagy are believed to play a protective role by promoting the clearance of damaged cellular components, potentially delaying or resisting the onset of sarcopenia." (PMID 39276001, 2024). "Therefore, we hypothesize that SFN may reduce mitochondrial oxidative stress levels and improve skeletal muscles function in sarcopenia through activation of the AMPK/Sirt1/PGC-1α/Nrf2 signaling pathway." (PMID 38629101, 2024). "In summary, our study establishes proof-of-concept to distinct the effect of berberine in sarcopenia IR, and provides strong evidence to support the hypothesis that berberine-induced SIRT1 triggers mitochondrial autophagy pathway and suppresses IR in sarcopenia." (PMID 37483428, 2023). "As a nicotinamide adenine dinucleotide (NAD+)–dependent histone deacetylase, sirtuin 1 (SIRT1) plays an important role in mitochondrial function and aging, and its activation can effectively reduce sarcopenia." (PMID 41383117, 2025). "Within skeletal muscle, the SIRT1/PGC‐1α signalling pathway is thought to collaboratively mitigate mitochondrial dysfunction and alleviate sarcopenia." (PMID 41383117, 2025). "In the two zebrafish sarcopenia models mentioned earlier, there was an alteration in mitochondrial fusion and fission events and a reduction in the AMPK/SIRT1/PGC-1α biogenesis pathway." (PMID 38892357, 2024). "In conclusion, this study found that EA combined with SFN mediated the repair of mitochondrial damage through activation of the AMPK/Sirt1/PGC-1α pathway, thereby alleviating skeletal muscles morphology and function in sarcopenia." (PMID 38629101, 2024). "Further studies are warranted to demonstrate the direct causal relationships between SIRT1 and autophagy, as well as SIRT1 and EEF1E1, and their roles in sarcopenia and cellular senescence." (PMID 39276001, 2024). "Moreover, BCAAs supplementation appears to improve lifespan, mitochondrial biogenesis (via SIRT1) and protein synthesis (via mTOR) in middle-aged mice, and to provide benefits for muscle mass, strength and protein synthesis rates in older subjects with pre-sarcopenia or sarcopenia." (PMID 36678201, 2023). "In sarcopenia patients, the NAD+ levels was reduced, while AMPK can elevate NAD+ levels and thus activate NAD+-dependent SIRT1." (PMID 34881083, 2021). "Previous studies also demonstrated that ADPN and AdipoR1 regulate the expression and activation of PPARγcoactivator-1α [PCG-1α], a key component of sarcopenia, by Ca2+ signalling, AMP-activated protein kinase (AMPK), and SIRT1." (PMID 32612097, 2020). "The hypothesis is that genes involved in epigenetic modifications, such as SIRT1, SIRT3, SIRT6, FOXO1, FOXO3A, DNMT3A, and ELAVL1, are critical for the development of sarcopenia and could be used as biomarkers for the diagnosis and monitoring of the disease." (PMID 40034697, 2025). "However, it is certain that novel modulators targeting SIRT1 and SIRT3 will be explored in the near future, which requires further unravelling the molecular pathway involved in frailty and its component sarcopenia." (PMID 36818553, 2023).
sarcopenia (continued). "Moreover, inhibition of SIRT1 is necessary for Toll-like receptor 9 (TLR9) dependent muscle fibrosis and sarcopenia in aged mice." (PMID 36818553, 2023). "In patients suffering from sarcopenia, FOXO3A mRNA level did not correlate with other analyzed genes, while in the geriatric control group, FOXO3A expression correlated with the SIRT genes (SIRT1 r=0.56, p=0.004; SIRT3 r=0.48, p = 0.015; and SIRT6 r=0.58, p=0.002)." (PMID 40034697, 2025).
endometriosis (36 papers, 2017 to 2026). The growth of functional endometrial tissue in anatomic sites outside the uterine body. "Mouse models have shown that overexpression of SIRT1 associated with oncogene activation contributes to the pathogenesis of endometriosis, but the underlying reason remains elusive." (PMID 35853978, 2022). "The role of SIRT1 in endometriosis was previously demonstrated in mice and humans, which suggests that an increase in SIRT1 expression is associated with oncogene KRAS activation and contributes to progesterone resistance in endometriosis." (PMID 35853978, 2022). "We recently described the association of BCL6 and SIRT1 as potential mediators of progesterone resistance in women with endometriosis." (PMID 34698105, 2021). "Our study explored the utilization of B-Cell Lymphoma 6 (BCL6) and Sirtuin 1 (SIRT1) as potential biomarkers in serum, plasma, urine, and cervical mucus for a non-invasive diagnostic test for endometriosis." (PMID 34698105, 2021). "A planned clinical trial (NCT04184323) will seek to explore inhibition of SIRT1 by EX-527 as a possible treatment for the inflammation associated with endometriosis." (PMID 34744791, 2021). "For this reason, SIRT1 protein was investigated as a potential diagnostic biomarker for endometriosis." (PMID 34698105, 2021). "Furthermore, high levels of Sirtuin 1 in endometriosis lesions appeared to cause further aggravation of endometriosis symptoms." (PMID 40792071, 2025). "In summary, this is the first time that non-mutated KRAS activation has been shown to be strongly correlated with endometrium-associated endometriosis and that this activation triggers specific changes in histone deacetylase, SIRT1 which we postulate is a key driver of P4 resistance." (PMID 28754906, 2017). "Interestingly, high Sirtuin 1 levels in endometriotic lesions seemed to cause further disease aggravation, whereas the Sirtuin 1 inhibitor EX-527 restored implantation and inhibited the development of endometriosis in mice." (PMID 37174627, 2023). "Thus, we hypothesized that escape from senescence mediated by SIRT1 is associated with the epithelial to mesenchymal transition in endometriosis." (PMID 35853978, 2022). "SIRT1, another histone modifier, is significantly upregulated in both the eutopic ESCs and EECs of endometriosis patients compared to controls." (PMID 40072055, 2025). "In 2022, the same research team studied the role of NAD + dependent class III HDAC Sirtuin 1, a stress-response and chromatin-silencing factor, showing notable increase in Sirtuin 1 expression in epithelial and stromal cells from endometriosis patients." (PMID 40792071, 2025). "Bushen Wenyang Huayu Decoction, a compound Chinese medicine preparation, inhibits autophagy by up-regulating SIRT1 (Sirtuin 1) and down-regulating FoXO-1 (Forkhead box protein O) expression in endometriosis via the SIRT1-FoXO-1 signaling pathway." (PMID 38397379, 2024). "This is based, in part, on evidence that endometrial biopsy-based testing for BCL6 and SIRT1 is predictive for the presence of endometriosis in women with infertility." (PMID 38999962, 2024). "SIRT1 was largely overexpressed in patients with endometriosis in comparison to healthy women, the expression correlating with the severity of endometriosis." (PMID 38612425, 2024). "In endometriosis and adenomyosis, iron overload inhibits cell proliferation and promotes autophagic cell death via PARP1 (Poly (ADP-Ribose) Polymerase 1)/SIRT1 (Sirtuin 1) signaling in endometriosis and adenomyosis." (PMID 38397379, 2024). "SIRT1, a histone deacetylase, has also been shown to be co-expressed with BCL6 and contribute to the inflammatory response associated with endometriosis." (PMID 38999962, 2024). "This aberrant Sirtuin 1 activation was further confirmed in a primate model of endometriosis progression." (PMID 37174627, 2023).